STS (steroid sulfatase)
Diseases named in the same sentence as STS in open-access papers (continued):
Sharing a sentence is not in itself a finding about the gene and the disease.
STS also shares sentences with these, for which no sentence is quoted: colorectal cancer (4 papers); ichthyosis vulgaris (4); genetic disorder (3); trichinellosis (3); depression (2); hypospadias (2); schizophrenia (2); adenomyosis (1); Arrhythmia (1); Arthritis (1); clear cells ovarian carcinoma (1); cognitive decline (1); colon adenocarcinoma (1); Corneal Dystrophies (1); corneal opacities (1); cryptorchidism (1); disseminated candidiasis (1); dyschondrosteosis (1); epithelial ovarian tumors (1); experimental autoimmune encephalomyelitis (1); gynecological cancers (1); hereditary neuropathy with liability to pressure palsies (1); Hyperkeratosis (1); hypoparathyroidism (1); infantile spasms (1); invasive carcinoma (1); kidney failure (1); lymph node metastases (1); Menkes disease (1); Multiple sulfatase deficiency (1).
A further 10 diseases each share a sentence with STS in 1 paper.